GPR119 (G protein-coupled receptor 119)
Diseases named in the same sentence as GPR119 in open-access papers (continued):
Sharing a sentence is not in itself a finding about the gene and the disease.
Insulin resistance (5 papers, 2013 to 2025). Increased resistance towards insulin, that is, diminished effectiveness of insulin in reducing blood glucose levels. "Recently, several GPCRs involved in the development of insulin resistance and pancreatic β-cell dysfunction, such as GPR119, GPR146, GPR40, GPR120, and TGR5, have received attention as targets for therapeutic interventions in diabetic patients." (PMID 35885041, 2022). "The agonist-induced GPR119/incretin axis can reduce stearoyl-coA desaturase -1(SCD-1) mRNA levels by attenuating insulin resistance, leading to decreased liver adipogenesis." (PMID 34233623, 2021). "Therefore, our overall and main conclusion based on these results is that GPR119 activation seems a weak tool to improve glycemia in the setting of insulin resistance." (PMID 23781322, 2013). "The insulin secretion due to GPR119 activation in insulin resistance was accompanied by significantly increased plasma levels of intact GLP1 already after 5 min (8.6±1.2 vs 3.7±0.9 pg/ml, P=0.004) and levels stayed significantly elevated after 20 min (1.2±0.2 vs 0.6±0.2 pg/ml, P=0.05)." (PMID 23781322, 2013). "The GPR119/incretin axis may have a protective effect on MAFLD through a series of physiological effects by attenuating insulin resistance, reducing fat production, reducing dietary intake, reducing weight gain, increasing cholesterol outflow, and interacting with intestinal microbes." (PMID 34233623, 2021). "Hence, in the setting of insulin resistance, it can therefore not be concluded whether a GPR119-mediated increase in GIP levels is causing the rise in glucagon after the current meal challenge." (PMID 23781322, 2013). "Terazosin treatment did not enhance glucose intolerance and insulin resistance in GPR119−/− mice, lower fasting blood glucose and serum insulin levels, or alleviate weight loss." (PMID 39413003, 2025). "Only a few studies exist on GPR119, free fatty acid receptor 1 (FFAR1/GPR40) and 4 (FFAR4/GPR120), and the bile acid receptor GPBAR1 (TGR5) as a developer of insulin resistance and β-cell dysfunction, receiving particular attention as targets for therapeutic interventions in diabetic patients." (PMID 35885041, 2022). "In conclusion, we suggest that the normal adaptive response of the β-cell to insulin resistance involves an upregulation of the incretin system manifested as both increased islet GLP1R protein levels and enhanced GPR119-activated GLP1 secretion, resulting in improved β-cell insulin secretion." (PMID 23781322, 2013).
fatty liver disease (4 papers, 2018 to 2021). A reversible condition wherein large vacuoles of triglyceride fat accumulate in liver cells via the process of steatosis. "Conclusively, ligands of GPR119 attenuated hepatic steatosis by inhibiting SREBP-1-mediated lipogenesis." (PMID 31121839, 2019). "Recent results have demonstrated strong in vivo evidence for protection against development of fatty liver by GPR119 agonist APD668 (4-[[1-[2-fluoro-4-(methylsulfonyl)phenyl]-1H-pyrazolo[3,4-d]pyrimidin-4-yl]oxy]-1-piperidinecarboxylic acid,1-methylethyl ester) in a mouse model of NASH." (PMID 31121839, 2019). "Although the role of GPR119 activation in hepatic steatosis and its precise mechanism has not been investigated, the GPR119 ligand alleviates hepatic steatosis by inhibiting sterol responsive element binding protein-1-mediated lipogenesis in hepatocytes." (PMID 32168769, 2020).
Crohn disease (3 papers, 2021 to 2025). A gastrointestinal disorder characterized by chronic inflammation involving all layers of the intestinal wall, noncaseating granulomas affecting the intestinal wall and regional lymph nodes, and transmural fibrosis. "Transcript levels of CB1 and GPR119 are decreased in Crohn’s disease patients, indicating the significant role that CB1 and GPR119 agonists play in intestinal inflammation." (PMID 36294963, 2022). "In addition, levels of GPR119 and CB1 transcripts were decreased in patients with Crohn’s disease, implying the significance of OEA and GPR119 in inflammatory bowel diseases." (PMID 33494185, 2021).
acne (2 papers, 2021 to 2022). An inflammatory process of the sebaceous glands which is characterized by comedones, nodules, papules and/or pustules on the skin. "GPR119 expression was downregulated in the sebaceous glands of patients with acne, implying OEA/GPR119 signaling as a positive regulator of sebocyte differentiation." (PMID 33494185, 2021). "However, the fact that prolipogenic GPR119 is downregulated in the sebaceous glands of acne patients seems to contradict the acne-promoting effect of GPR119." (PMID 36552866, 2022). "In addition, GPR119, which can be activated by OEA, has been found to be downregulated in the sebaceous glands of acne patients." (PMID 36552866, 2022).
atherosclerosis (2 papers, 2018). A disease characterized by the build-up of fatty material and calcium deposition in the arterial wall resulting in partial or complete occlusion of the arterial lumen. "In addition, GPR119 expression is upregulated by oxidized low-density lipoprotein in THP-1 human monocyte cell line, and GPR119 overexpression inhibits the development of atherosclerosis in apoE-null mice." (PMID 30497501, 2018).
hepatoma (2 papers, 2016 to 2018). "We investigated in vitro and in vivo combination effects of GPR119 agonists with TKIs in breast cancer and hepatoma cells, and clarified the mechanistic basis for the anticancer effects of GPR119 agonists, focusing on autophagy inhibition." (PMID 30497501, 2018). "When we determined GPR119 mRNA expression in HepG2, SNU-449 and SK-Hep1 hepatocellular carcinoma cell lines, GPR119 mRNA was similarly detected in HepG2 and SNU-449 cells, but its expression level was relatively low in SK-Hep1 cells." (PMID 30497501, 2018). "Interestingly, it has been recently demonstrated that LPI can also activate GPR119 in RH7777 rat hepatoma cells stably expressing human GPR119." (PMID 26784247, 2016).
hyperlipidaemia (2 papers, 2014 to 2021). "For example, OEA decreases food intake and lowers hyperlipidaemia in obese rats via PPARα activation and both OEA and PEA can stimulate insulin and GLP-1 secretion via activation of GPR119." (PMID 24593280, 2014).
insulinoma (2 papers, 2013 to 2022). "To confirm the direct effects of MW1219 on pancreatic β-cells, we examined glucose-stimulated insulin secretion by mouse pancreatic MIN6 insulinoma cells which endogenously express GPR119." (PMID 23704946, 2013). "Oleoyl lysophosphatidylcholine (LPC 18:1) binds to the membrane receptor of GPR119 on β-cells, regulating insulin secretion through a protein kinase A (PKA)-related signaling pathway, and promotes glucose-stimulated insulin secretion in murine NIT-1 insulinoma cells." (PMID 36557202, 2022).
melanoma (2 papers, 2014 to 2019). A malignant, usually aggressive tumor composed of atypical, neoplastic melanocytes. "Expression of CB1, CB2, GPR18, GPR55 and GPR119 were identified in A2058 human amelanotic melanoma cell line." (PMID 30845666, 2019). "First, we identified the presence of CB1, CB2(A), GPR18 (transcriptional variant 1) and GPR55 receptors in brain endothelial cells, while melanoma cells expressed CB1, CB2(A), GPR18 (transcriptional variants 1 and 2), GPR55 and GPR119." (PMID 24815068, 2014). "Since besides CB1 and GPR55, AM251 can also target GPR18, one might speculate that modulating activity of this receptor may be responsible for the beneficial effects, especially, since GPR18 (as well as GPR119) was found to be overexpressed at the mRNA level in melanomas as compared to nevi." (PMID 30845666, 2019).
type 1 diabetes (2 papers, 2016 to 2024). "Therefore, GPR119 agonists may qualify as therapeutic agents to regenerate β-cells and to increase β-cell mass in islet transplanted patients with type 1 diabetes." (PMID 27413754, 2016).
acute monocytic leukemia (1 paper, 2019). Acute monoblastic leukemia (AML-M5), is one of the most common subtypes of acute myeloid leukemia (AML) that is either comprised of more than 80% of monoblasts (AML-M5a) or 30-80% monoblasts with (pro)monocytic differentiation (AML-M5b). "Studies have demonstrated that Ox-LDL significantly induced lincRNA-DYNLRB2-2 expression, which promoted ABCA1-mediated cholesterol efflux and inhibited inflammation through G protein-coupled receptor 119 (GPR119) in acute monocytic leukemia (THP-1) macrophage derived foam cells." (PMID 31011482, 2019).
breast carcinoma (1 paper, 2018). "Here, we found that GPR119 was ubiquitously expressed in human breast cancer cell lines and tumor tissues." (PMID 30497501, 2018). "The data suggest that GPR119 aognist with gefitinib synergistically inhibits proliferation of breast cancer cells." (PMID 30497501, 2018). "We further quantified GPR119 mRNA expression in 11 breast cancer cell lines and MCF10A mammary epithelial cell line by real-time qPCR analyses." (PMID 30497501, 2018). "We observed that GPR119 expressed in human breast cancer cell lines and tumor tissues, and GPR119 agonists with gefitinib additively suppressed the growth of breast cancer cells and induced intrinsic apoptosis." (PMID 30497501, 2018). "GPR119 expression was assessed by real-time qPCR and immunohistochemistry in human breast cancer cell lines and breast cancer tissues." (PMID 30497501, 2018). "Thus, GPR119 was constitutively expressed in human breast cancer." (PMID 30497501, 2018). "Hence, we assessed whether GPR119 agonist provides synergistic benefit with EGFR-TKI in human breast cancer." (PMID 30497501, 2018). "We further tested the combined effects of GPR119 agonist with gefitinib on cell proliferation of MDA-MB-468 (a TNBC cell line) and SK-BR-3 cells (a Her2+ and ER+ breast cancer cell line)." (PMID 30497501, 2018). "Cotreatment with GPR119 agonist (MBX-2982 or GSK1292263) significantly potentiated gefitinib-induced cell growth inhibition in gefitinib-insensitive MCF-7 and MDA-MB-231 breast cancer cells." (PMID 30497501, 2018). "The data demonstrate that GPR119 agonist inhibits autophagosome formation in cancer cells treated with EGFR-TKI and possess anticancer effects against breast cancer." (PMID 30497501, 2018). "GPR119 agonists reduced mitochondrial OXPHOS and stimulated glycolysis in breast cancer cells, with consequent overproduction of lactate that inhibited autophagosome formation." (PMID 30497501, 2018). "Immunohistochemistry showed that 19 samples from 49 human breast cancer tissues were GPR119 positive, but there were no remarkable changes in GPR119 expression depending on TMN stages and tumor stages of patients or estrogen receptor (ER)-α." (PMID 30497501, 2018). "Although significant differences were not seen between benign and malignant cancer tissues, GPR119 mRNA was identified from human breast cancer tissue datasets." (PMID 30497501, 2018). "Because a previous study has reported that increased glycolysis and lactate production triggers breast cancer cell stemness and tumor growth in MCF-7 cells, GPR119 activation could be related with cancer cell stemness." (PMID 30497501, 2018).
epilepsy (1 paper, 2025). A brain disorder characterized by episodes of abnormally increased neuronal discharge resulting in transient episodes of sensory or motor neurological dysfunction, or psychic dysfunction. "The orphan/atypical GPCRs (GPR55, GPR119, and GPR18) carry links to epilepsy and inflammatory hyper-excitability (GPR55), incretin biology and insulin release (GPR119), and tone in blood vessels with traffic of leukocytes (GPR18)." (PMID 41303442, 2025).
Hepatic fibrosis (1 paper, 2023). The presence of excessive fibrous connective tissue in the liver. "Mechanistic studies suggest that 2-OG activates HSCs to induce hepatic fibrosis by modulating MΦs through the GPR119/TAK1/NF-κB/TGF-β1 signaling pathway." (PMID 36646715, 2023).
pancreatic cancer (1 paper, 2022). "Similarly, GPR119 has been found overexpressed in pancreatic cancer and in silico analysis of the open-access databases indicate that GPR119 is a favourable prognostic factor (Human Protein Atlas)." (PMID 35204820, 2022).
metabolic disease (8 papers, 2015 to 2022). A congenital disorder (due to inherited enzyme abnormality) or acquired (due to failure of a metabolically important organ) disorder resulting from an abnormal metabolic process. "Agonists selectively targeting cannabinoid receptor-like G-protein-coupled receptor (GPCR) GPR119 hold promise for treating metabolic disorders while avoiding unwanted side effects." (PMID 36396650, 2022). "The detrimental effect of the decrease in oxidative/metabolic capacity warrants more studies before GPR119 agonists can treat metabolic diseases." (PMID 34943862, 2021). "Agonists selectively targeting GPR119 hold promise for treating metabolic disorders." (PMID 36396650, 2022). "Therefore, GPR119 becomes an attractive target for the development of novel therapeutics towards metabolic disorders, such as obesity and type 2 diabetes." (PMID 36396650, 2022). "An important family of G protein-coupled receptor (GPCR) ligands namely N-acyl amides produced by gut microbiota is shown to be agonists of receptors that have important functions for gastrointestinal and metabolic diseases, such as the endocannabinoid receptor GPR119." (PMID 34884651, 2021). "GPR119 agonists may have a promising role in the treatment of T2D and related metabolic disorders." (PMID 34943862, 2021). "However, as a Gas-coupled receptor, GPR119 has a single pathway of action that may provide only a small contribution to the attenuation of metabolic diseases, and there may be synergy between receptors of different coupling pathways." (PMID 34233623, 2021).
cancer (3 papers, 2018 to 2025). A tumor composed of atypical neoplastic, often pleomorphic cells that invade other tissues. "Mechanistically, CYP4X1/sEH-derived 14,15-EET-EA upregulates PD-L1, CXCL12, and TGF-β in cancer-associated fibroblasts (CAFs) via the GPR119-Gs/β-arrestin 2 signaling axis." (PMID 41276938, 2025). "Although its relevance in cancer is practically unexplored, the putative role of GPR119 as a cannabinoid receptor allows to consider its modulation for symptom management and cancer therapy." (PMID 33113952, 2020). "Our findings indicate that the combination of GPR119 agonist with TKI would be a possible therapeutic approach for cancer chemotherapy." (PMID 30497501, 2018). "Because autophagy is crucial for the survival of cancer cells exposed to TKIs, GPR119 agonists potentiated the anticancer effects of TKIs." (PMID 30497501, 2018). "Moreover, combination of GPR119 agonist with 4-hydroxytamoxifen in MCF-7 cells as well as with sorafenib in HepG2 cells enhanced the anti-cancer effect of each target therapy." (PMID 30497501, 2018). "Although autophagolysosome activity is likely to be amplified by physiologically acidic pH (< 6.4), GPR119 agonist-induced supraphysiological lactate production could suppress autophagosome formation and eventually induce cancer cell death." (PMID 30497501, 2018). "mRNA or protein expression of GPR119 was detected in 9 cancer cell lines and 19 tissue samples." (PMID 30497501, 2018). "To assess whether GPR119 agonist induces cancer cell stemness in MCF-7 cells, we performed spheroid formation assay in ultra-low attachment (ULA) plate condition." (PMID 30497501, 2018). "We found GEO datasets containing GPR119 transcript levels in various cancer cell types." (PMID 30497501, 2018). "Moreover, the coadministration of gefitinib with MBX-2982 did not reduce the tumor volume in xenografts implanted with shGPR119-MCF-7 cells, which imply that GPR119 signaling is required for anti-cancer effect of MBX-2982." (PMID 30497501, 2018). "Apoptosis induction and autophagy inhibition by a GPR119 agonist might be related to changes in cancer cell metabolism instead of canonical signaling pathway(s) of GRP119." (PMID 30497501, 2018). "Because the activation of p70S6K and 4EBP1 is important for mRNA translation, GPR119 agonsit-induced mTORC1 inhibition may lead to the depletion of protein synthesis in cancer cells." (PMID 30497501, 2018). "Thus, GPR119 agonist-mediated lactate production may lead to autophagy inhibition and potentiated cancer cell apoptosis with EGFR-TKI." (PMID 30497501, 2018). "Interestingly, the spheroid volume was significantly diminished by MBX-2982, which suggest that GPR119 agonist does not induce cancer cell stemness, rather inhibits spheroid formation." (PMID 30497501, 2018). "However, the function of GPR119 in cancer cells has not been studied." (PMID 30497501, 2018).
infection (2 papers, 2018 to 2021). The state of being infected such as from the introduction of a foreign agent such as serum, vaccine, antigenic substance or organism. "We established GPR119 knockdown cells by shRNA infection to assess whether autophagy inhibition by MBX-2982 was due to target receptor-mediated response." (PMID 30497501, 2018).
tumor (2 papers, 2016 to 2018). "GPR119 agonist-mediated lactate production could suppress the inflammatory immune cells producing tumor-promoting cytokines via GPR81 activation." (PMID 30497501, 2018). "Depending on the tumor’s origin, the tumor cells themselves express CB1 and CB2, which has been reviewed elsewhere, and possibly GPR119, the latter particularly in tumors of epithelial origin." (PMID 26875980, 2016).
neurodegenerative disease (1 paper, 2026). A disorder of the central nervous system characterized by gradual and progressive loss of neural tissue and neurologic function. "This is interesting because Gpr119 is known to play a role in the secretion of incretin hormones and incretins are currently under investigation to be potentially used as a new target in the treatment of neurodegenerative diseases." (PMID 41524247, 2026).
GPR119 also shares sentences with these, for which no sentence is quoted: fatty liver (2 papers); cognitive disorders (1); colitis (1); colon cancer (1); dyslipidemia (1); eating disorder (1); frontotemporal dementia (1); Glucose intolerance (1); Impaired glucose tolerance (1); inflammatory bowel disease (1); liver disease (1); testicular cancer (1).